HTRA3 (HtrA serine peptidase 3)
Diseases named in the same sentence as HTRA3 in open-access papers (continued):
Sharing a sentence is not in itself a finding about the gene and the disease.
tumor (continued). "Moreover, higher expression of POSTN and HTRA3 positively correlated with infiltration of neutrophils, which can promote tumor progression." (PMID 35676936, 2022). "HTRA3 was downregulated in tumor cells compared with normal counterpart." (PMID 34217320, 2021). "Like HtrA2, HTRA3 expression is variable in cancer depending on the tumour type." (PMID 34639128, 2021). "HTRA3 is likewise detected in most tumours except liver cancer." (PMID 34639128, 2021). "Pancreatic cancer has the highest HTRA3 expression compared to other tumours." (PMID 34639128, 2021). "The high similarity of the HtrA4 protein domain structure to that of HtrA1 and HtrA3 and implication of HtrA4 in oncogenesis suggested that it may function similarly to the HtrA1/3, which act as tumor suppressors and promote cell death." (PMID 31546993, 2019). "HTRA3 is a candidate tumor suppressor and the target of therapeutics currently in development." (PMID 29100308, 2017). "Our current data indicated that HTRA3 expression was downregulated in surgically excised cancer tissues compared to normal lung tissues, suggesting that HTRA3 may be an important tumor suppresser in NSCLC." (PMID 27166271, 2016). "Among the tumor specimens from these patients, 38 (48.7%) expressed HTRA3 protein." (PMID 27166271, 2016). "Since HtrA3 is downregulated in a number of cancers, it is proposed to be a tumor suppressor." (PMID 25248123, 2014). "Thus, the expression of HTRA3 might be tumor-type-specific, and this question needs further investigations." (PMID 32486357, 2020). "However, HTRA3 can promote tumor progression in other malignancies." (PMID 33425760, 2020). "Moreover, by using NSCLC cell lines, we further investigated whether HTRA3 influenced the progression of NSCLC by promoting or inhibiting tumor cell invasion." (PMID 27166271, 2016). "Thus, HTRA3 suppresses tumor cell invasiveness and may serve as a prognostic biomarker for postoperative recurrence or survival in NSCLC." (PMID 27166271, 2016). "Therefore, in this study, we further investigated whether the expression of HTRA3 in NSCLC cell lines would inhibit or promote tumor cell invasion." (PMID 27166271, 2016). "We validated the transcriptional expression of identified 6 key fibrosis factors (PCOLCE2, APOD, APOE, TIMP1, HTRA3 and MT1A) in tumor and normal tissues obtained from 20 PTC patients." (PMID 36387901, 2022). "LMO1, RP11-834C11.12, MAN1A2P1, HTRA3 and ESR1 were the top five differentially hypermethylated genes in primary tumours compared to NAT." (PMID 32971738, 2020). "Two of these genes, HTRA3 and STAC2, were found as the top five hypermethylated CGIs in primary tumour and LNM, respectively." (PMID 32971738, 2020). "HTRA3 might promote the instability of cytoskeleton, thereby regulating the EMT process of various tumor cells." (PMID 33425760, 2020). "Firstly, the pan-cancer analyses were performed to compare the expression of HTRA3 in the tumor samples of GTEx combined with TCGA and the corresponding normal samples of TCGA by Wilcoxon rank sum test." (PMID 33425760, 2020). "Another protein that has been associated with a poor outcome in Stage II and III CRC is the serine protease HTRA3 which was not detectable in the WT tumor proteome, but clearly elevated in the G12V (HTRA3↑WT; 19 peptides and 68 PSM)." (PMID 31805664, 2019). "An increase in serine proteases HTRA3, myeloblastin and lactotransferrin in all stages and metalloproteinases (MMP-9, ADAMTS4 and neutrophil elastase) in CC NM and CC M, supports degradation of the stroma surrounding the tissues as the tumor progresses." (PMID 31889941, 2019).
tumor (continued). "The majority of previously published studies concerning the expression of HTRA3 in tumor tissue did not focus on the HtrA3 isoforms, but analyzed overall expression, including recently published results based on IHC analysis of HtrA3 content in colorectal tissue." (PMID 32486357, 2020). "Second, since HTRA3 is downregulated and proposed to be a tumor suppressor in NSCLC, stimulating HTRA3 activity may be a potential therapeutic strategy with which to inhibit tumor malignancy." (PMID 27166271, 2016). "In detail, tumor relapse was observed in 0 (0%) of the six cases with high expression of HTRA3, 10 (31.2%) of the 32 cases with low expression and 14 (35.0%) of the 40 HTRA3-negative cases." (PMID 27166271, 2016). "Two genes were over-expressed in the aggressive human specimens compared with the non-aggressive tumor, CCL18 (p = 0.03) and HTRA3 (p = 0.04)." (PMID 29100308, 2017).
cancer (21 papers, 2008 to 2024). A tumor composed of atypical neoplastic, often pleomorphic cells that invade other tissues. "The expression of HTRA3 has been found to be diminished or even lost in several cancer cell lines and tumors, which was associated with poor response to chemotherapeutic treatment and higher risk of postoperative recurrence in patients with lung cancer." (PMID 32486357, 2020). "Genes encoding for proteins TPRKB, T-Complex 1 (TCP1), Olftactomedin 1 (OLFM1), LDOC1 and HTRA3 have been implicated positive or negatively in cancer progression." (PMID 18793431, 2008). "In particular, HtrA1 and HtrA3 have been suggested as tumor suppressors, because they are down-regulated in a number of cancers and this reduction is suggested to promote tumorigenesis." (PMID 28676687, 2017). "This is in agreement with the finding that exogenous full-length HtrA3L is more efficient than HtrA3-ΔPDZ in promoting the apoptosis of cancer cells." (PMID 26110759, 2015). "HtrA3 is also down-regulated in a number of cancers (eg. ovary, endometrium and lung) and has been suggested to inhibit transforming growth factor-β signaling." (PMID 25248123, 2014). "HtrA3 is thus proposed to be a tumour suppressor and a potential therapeutic aid in cancer treatment." (PMID 23049902, 2012). "Four genes are hypermethylated in all 9 tested cancers, while for SST (7 of 9 carcinomas), HTRA3 (1 of 9 carcinomas) and NPTX1 (5 of 10 carcinomas) a fraction of the tested carcinomas is hypermethylated." (PMID 19025626, 2008). "And HTRA3 is a potential therapeutic target involved in various cancers." (PMID 33425760, 2020). "HTRA3 negatively regulates trophoblast cell invasion and migration, raising the possibility that HTRA3 could have a similar effect on cancer cell invasion and metastasis." (PMID 27166271, 2016). "On the other hand, it has been suggested that the downregulation of LDOC1 and HTRA3 genes may play an important role in the development and/or progression of some cancers." (PMID 18793431, 2008). "Htra3 expression has been shown to be down-regulated with increasing grades in endometrial and ovarian cancer, suggesting that Htra3 might also be a target of cancer treatment." (PMID 35672400, 2022). "Hypoxia leads to a decrease in HtrA3, which may promote cancer progression." (PMID 33462352, 2021). "Similarly to HtrA1 and HtrA2, HtrA3 exhibits proapoptotic function in certain pathological conditions; upon action of chemotherapeutic drugs, the mitochondria-localized HtrA3 is released into the cytosol and it participates in the stimulation of mitochondria-mediated apoptosis of cancer cells." (PMID 32486357, 2020). "However, the high similarity of the HtrA4 protein domain structure to that of HtrA1 and HtrA3, and implication of HtrA4 in oncogenesis suggest that it may function similarly to HtrA1/3 in promoting cancer cell death." (PMID 31546993, 2019). "Thus, it is possible that HTRA3 inhibits TGF-β function in its activation of cancer cells motility." (PMID 27166271, 2016). "In contrast, FIGN, HTRA3 and BDNF have been reported in cancer, EMT, invasion/migration process or poor outcome of patients, but our study for the first time links them to methylation status." (PMID 32971738, 2020). "The role of HTRA3 is weakened, and transforming growth factor β1 effectively promoted EMT without HTRA3 brakes in the later stage of cancer." (PMID 33425760, 2020). "Moreover, it was shown that a fraction of full-length HtrA3, despite the lack of mitochondrial targeting sequence, was located in mitochondria, and in cancer cell lines treated with chemotherapeutic HtrA3, it was translocated from the mitochondria to the cytosol." (PMID 31546993, 2019).
infection (2 papers, 2023 to 2024). The state of being infected such as from the introduction of a foreign agent such as serum, vaccine, antigenic substance or organism. "The recovered pigs had a significant down-regulation of HTRA3 and GFPT2 of up to 12.85 and 9.57 fold, respectively, before the infection challenge compared to recovered pigs." (PMID 38467747, 2024).
HTRA3 also shares sentences with these, for which no sentence is quoted: lymph node metastasis (2 papers); acute myeloid leukemia (1); Arthritis (1); cervical cancer (1); head and neck squamous cell carcinoma (1); hematologic malignancies (1); kidney tumors (1); Myocardial fibrosis (1); ovarian tumors (1); respiratory allergy (1).